CXCR3 (C-X-C motif chemokine receptor 3)
Diseases named in the same sentence as CXCR3 in open-access papers (continued):
Sharing a sentence is not in itself a finding about the gene and the disease.
cardiovascular diseases (12 papers, 2014 to 2025). "Levels of plasma IP-10 and/or its receptor (CXCR3) are increased in a number of cardiovascular disorders." (PMID 32881912, 2020). "Recent evidence from us and others has revealed the importance of the CXCL10/CXCR3 axis in cardiovascular diseases." (PMID 27795961, 2016). "Following are some cardiovascular diseases with known CXCR3 involvement." (PMID 35794867, 2022). "Here our focus will be on the aspect of CXCR3 in neurological and cardiovascular diseases." (PMID 35794867, 2022). "Moreover, earlier findings that anti-CXCR3 antibodies may be a marker of cardiovascular disease increase their clinical importance and future opportunities to develop drugs targeting them." (PMID 39768675, 2024). "Similar ligands have been designed that exert CXCL11-like actions following an attachment to CXCR3 but their applications on cardiovascular diseases in experimental rodent models has yet to be elucidated, a fact that may be due to the short in vitro half-life of CXCL10." (PMID 34835155, 2021). "The specific targeting of CXCR3 may possibly be more effective for the therapy of chronic cardiac inflammation in combination with approaches enhancing Treg numbers and activity, which are generally reduced in cardiovascular diseases." (PMID 34835155, 2021). "Targeting CXCR3 might be more effective in treating chronic heart inflammation in combination with approaches to enhance Treg numbers or activity, which are generally reduced in cardiovascular diseases." (PMID 27795961, 2016). "The chemokine receptor CXCR3 and its agonist CXCL10 are potential drug targets to treat various cardiovascular diseases." (PMID 27795961, 2016). "After binding to its receptor CXCR3, CXCL10 evokes a range of inflammatory responses: key features in cardiovascular disease (CVD)." (PMID 24868552, 2014). "In addition, due to the significant positive correlation between LncRNA-HIX003209 and CXCR3, it can be said that LncRNA-HIX003209 probably also plays a pathological role in the development of cardiovascular disorders in RA patients." (PMID 39281435, 2024). "Biased agonists have been developed that exert CXCL11-like actions at CXCR3 but have not as yet been assessed in experimental models of cardiovascular diseases." (PMID 27795961, 2016).
infectious disease (11 papers, 2014 to 2022). A disorder directly resulting from the presence and activity of a microbial, viral, or parasitic agent in humans. "CXCL11 and its receptor, CXCR3, are likely to be associated with important inflammatory diseases of livestock, as well as with protective immunity to infectious diseases and tumors." (PMID 27098998, 2016). "The activation of CXCL10/CXCR3 is linked to many infectious diseases." (PMID 35604176, 2022). "Our KEGG pathway enrichment analysis also showed that infectious disease-related pathways were activated via CXCR3 during T. gondii infection." (PMID 34835465, 2021). "Hence, further studies are needed to explore the downstream and upstream signaling pathways regulating chemokines and their receptors ligands, particularly CXCL10 and their receptor ligands CXCR3, with the aim to exploit new methods to control infectious diseases mediated by theses chemokines." (PMID 28018321, 2016). "Through binding to its receptor CXCR3, CXCL10 mediates the recruitment and activation of monocytes, T cells and natural killer cells, and therefore plays critical roles in defense against infectious diseases." (PMID 30620752, 2019).
bacterial infection (10 papers, 2012 to 2024). "In this organism, Cxcr3.2 and Cxcr3.3 copies, both expressed on macrophages, have been shown to coordinate their migration during bacterial infection by functioning antagonistically." (PMID 35720349, 2022). "CXCR3 is important for NK cell trafficking to the lung both in homeostasis and in bacterial infection." (PMID 29719539, 2018). "As a result, CXCR3−/− mice resolved bacterial infection less efficient than WT, but they had lessened tissue damage." (PMID 29552679, 2017). "The activation of NK T cells after CLP may facilitate intrahepatic trafficking since previous studies have shown that activation of CXCR3 functions to regulate the migration of NK T cells within the hepatic sinusoids during periods of bacterial infection." (PMID 22992408, 2012).
kidney disease (7 papers, 2013 to 2024). "These pathways are altered in kidney disease and are linked to the production of vascular endothelial growth factor, erythropoietin, adiponectin, interleukin (IL)-18, IL-23, and chemokines that bind CXCR3, CXCR4, and/or CXCR7." (PMID 33676416, 2021). "CXCL10/CXCR3 expression was analyzed in two experimental models of nephrotic syndrome, puromycin aminonucleoside nephropathy (PAN) and anti-nephrin antibody-induced nephropathy (ANA), both with slit diaphragm (SD) dysfunction resulting in proteinuria." (PMID 32089645, 2020). "Elevated CXCL10 and CXCR3 levels were detected in various renal diseases and correlated with disease progression." (PMID 32089645, 2020). "Certain kidney diseases involve CXCR3 in their development, with glucocorticoids having been shown to diminish CXCR3+ T cell influx during c-ANCA vasculitis and cause increased CXCR3+ T cell numbers in kidney biopsies from p-ANCA vasculitis patients, indicating a poorer prognosis." (PMID 39768675, 2024). "High expressions of chemokines and their receptors in the infiltrating immune cells are recognized as the characteristic events in the progression of DN and CXCR3, and its ligands, CXCL9, CXCL10, and CXCL10 are the well-known risk factors for inflammatory-based kidney diseases." (PMID 36686486, 2022). "In this review, we summarize the structures and biological functions of CXCL10 and CXCR3, focusing on the important role of CXCL10 in the pathogenesis of kidney disease, and provide a theoretical basis for CXCL10 as a potential biomarker and therapeutic target in human kidney disease." (PMID 32089645, 2020).
neurological disease (6 papers, 2012 to 2025). "The activity of IFN-γ-inducible CXC chemokines mediated via CXCR3 was firstly investigated using a model of DENV-induced neurological disease in wild-type (WT), CXCR3-or CXCL10/IP-10 deficient mice." (PMID 22815692, 2012). "Based on these findings, CXCL10 has been speculated as a plasma inflammatory biomarker of immune activation in both viremic and aviremic HIV patients on cART therapy and, was found to be associated with a more rapid HIV/SIV neurological disease progression via the influx of CXCR3+ cells in the CNS." (PMID 34527676, 2021). "Microglia–astrocyte interactions and the upregulation of CXCL10 are common features in various neurological disorders and aging, associated with increased numbers of CD8+CXCR3+ TRM cells." (PMID 40404995, 2025). "The roles of CXCR3 and its ligands in chronic neuroinflammatory models have been widely studied, and they constitute the focus of CXCR3 research in the field of nervous system diseases." (PMID 39429695, 2024). "It has been shown that CXCR3 and its ligands are expressed at high levels in CSF and peripheral blood of patients with neurological disorders and are potentially useful regulators of neuroinflammatory response." (PMID 35702353, 2022). "This article explores the relationships of CXCR3 in the CNS and PNS with various diseases and provides abundant theoretical evidence for research into nervous system diseases." (PMID 39429695, 2024). "In recent years, CXCR3 has also been the subject of growing interest in the context of non-neoplastic neurological disorders, where it exerts a pivotal influence on the modulation of inflammatory processes." (PMID 40781073, 2025).
immune diseases (5 papers, 2011 to 2024). "CXCR3 and its ligands havebeen implicated in a large variety of inflammatory and immune disorders." (PMID 21533215, 2011). "We thus presume that the upregulated DEGs such as Cav1, CD200R1, TNFRSF17 and CXCR3 and downregulated DEGs such as EIF1AY and DDX3Y in healthy female may be involved in gender predominance of some immune diseases." (PMID 24741625, 2014). "Moreover, the upregulated DEGs (Cav1, CD200R1, TNFRSF17, and CXCR3) and downregulated DEGs (EIF1AY and DDX3Y) in healthy female may be involved in gender predominance of some immune diseases." (PMID 24741625, 2014).
adenocarcinoma (3 papers, 2012 to 2023). A common cancer characterized by the presence of malignant glandular cells. "For adenocarcinoma with concomitant active TB, significantly higher expression of CD3 and CXCR3 are also noted." (PMID 22438899, 2012).
prostatitis (3 papers, 2016 to 2024). An infectious or non-infectious inflammatory process affecting the prostate gland. "We further confirmed this observation by demonstrating a protective effect of CXCR3 genetic deletion against FFC diet-induced liver inflammation, injury and fibrosis." (PMID 27349927, 2016).
cardiac diseases (2 papers, 2022 to 2026). "Thus, CXCR3 ligands have great potential as biomarkers for heart diseases, and it would be helpful to discern the pathways involved to target the CXCR3 signaling axes as a treatment modality." (PMID 35794867, 2022).
central nervous system diseases (2 papers, 2021 to 2022). "Two of them are Cxcl9 and Cxcl11, which are involved in Th1-type response, correlating with T-cell infiltration; the comprehension of CXCR3 (C-X-C Motif Chemokine Receptor 3)/CXCL9′s binding mechanism of action is considered crucial for the treatment of central nervous system diseases." (PMID 35806178, 2022).
neurodegenerative disease (2 papers, 2012 to 2025). A disorder of the central nervous system characterized by gradual and progressive loss of neural tissue and neurologic function. "CXCR3 plays a significant role in neurodegenerative diseases." (PMID 40786052, 2025).
respiratory diseases (2 papers, 2022 to 2023). "These CXCR3+ CD8+T cells could confer a degree of protection by localization to infected tissue compartments, and provide site-specific responses, which are known to be important in protection against respiratory disease." (PMID 36590902, 2023).
benign tumors (1 paper, 2018). "Here, we characterized the expression pattern of CXCR3 variants and their ligands in benign tumors and PTC." (PMID 29416784, 2018). "We report a progressive increase in protein balance of CXCR3 variants when comparing control tissue to benign tumors and malignant thyroid neoplasia where CXCR3A was always the predominant isoform." (PMID 29416784, 2018). "In benign tumors, nMPTC and MPTC tissues, both CXCR3 variants showed a significant increase when compared to B-CLT (CXCR3A: p=0.0050, p=0.0014 and p=0.0353; CXCR3B: p=0.001, p<0.0001 and p<0.0001)." (PMID 29416784, 2018).
CXCR3 also shares sentences with these, for which no sentence is quoted: coronary artery disease (4 papers); juvenile idiopathic arthritis (4); primary biliary cholangitis (4); chronic B-cell lymphocytic leukemia (3); autoimmune uveitis (2); biliary cirrhosis (2); cardiac hypertrophy (2); Cerebral ischemia (2); chronic hepatitis (2); colon (2); giant cell arteritis (2); head and neck cancer (2); inclusion body myositis (2); interstitial cystitis (2); leukoplakia (2); metastatic cancer (2); mycobacterial infection (2); papillary thyroid cancer (2); polymyalgia rheumatica (2); primary immunodeficiencies (2); T-cell leukemia (2); viral hepatitis (2); acute angle closure glaucoma (1); acute lymphocytic leukemia (1); acute myocardial infarction (1); adult T-cell leukemia/lymphoma (1); adult-onset Still disease (1); age-related macular degeneration (1); airway hyperresponsiveness (1); Airway obstruction (1).
A further 108 diseases each share a sentence with CXCR3 in 1 paper.